KRAS (KRas proto-oncogene, GTPase)
Diseases named in the same sentence as KRAS in open-access papers (continued):
Sharing a sentence is not in itself a finding about the gene and the disease.
pancreatic cancer (continued). "In a study of four pancreatic cancers (3 with KRAS mutation), a combination of L-778,123 and RT at dose level 1 showed acceptable toxicity." (PMID 36313934, 2023). "Increased SRC expression positively correlates with chemoresistance in human pancreatic cancer cell lines, while oncogenic KRAS mutations induce a SRC-dependent amplification loop that promotes metastasis and therapy resistance in human PDAC tumors." (PMID 37120696, 2023). "In this section, we mainly list the treatment of several cancers commonly carrying KRAS mutations, such as pancreatic cancer, NSCLC, and CRC." (PMID 37250144, 2023). "Detection of KRAS mutation in ctDNA is expected to be applied to the early diagnosis of pancreatic cancer." (PMID 37007078, 2023). "KRAS mutations, observed in more than 90% of pancreatic cancer patients, initiate tumorigenesis and drive neoplastic progression." (PMID 37108468, 2023). "Activating mutations in KRAS are a hallmark of pancreatic cancer, and are observed in approximately 95% of patients." (PMID 37120696, 2023). "The first genetic event that leads the earliest precancerous lesions to invasive pancreatic cancer is the mutational activation of KRAS." (PMID 37298264, 2023). "For example, in patients with advanced or metastatic pancreatic cancer, KRAS mutations in exosomal DNA are detected at a much higher rate than cfDNA." (PMID 36911396, 2023). "In a recent study, the presence of KRAS mutations in cfDNA from unresectable pancreatic cancer patients was strongly associated with unfavorable treatment results and suggested this molecular evaluation as biomarker early tumor progression." (PMID 37798621, 2023). "in 2016 demonstrated that co-occurring LKB1 and KRAS mutations in pancreatic cancer GEMMs elicit significant epigenetic changes stemming from aberrant activity in the serine metabolic axis." (PMID 37035141, 2023). "While in pancreatic cancer the vast majority of patients present with activating KRAS mutations and a KRAS WT group is therefore difficult to obtain, in non-small cell lung cancer (NSCLC) about half of the patients are usually WT." (PMID 36443441, 2023). "Data from NSCLC patients demonstrated that KRAS mutation is very low in NSCLC but high in pancreatic cancer, and that it has a significantly lower benefit from EGFR tyrosine kinase inhibitor." (PMID 36975494, 2023). "This is similar to other studies in literature where KRAS mutation is noted in around in 85-90% of pancreatic cancers." (PMID 37404765, 2023). "Activating mutations in KRAS drive more than 90% of pancreatic cancers and are thought to initiate a shift towards glycolysis to sustain rapid energy demand in the malignant tumor." (PMID 37990271, 2023). "The KRAS G12D mutation, which accounts for approximately 30% of all KRAS mutations in pancreatic cancer, drives expression of ICAM1 by acinar cells in vivo a mouse model, attracting macrophages to accelerate formation of pre-cancer pancreatic lesions." (PMID 37880707, 2023). "In this study, we found that CIB1 was widely co-expressed with KRAS mutation in pancreatic cancer cell lines and upregulated in tumor samples." (PMID 37187730, 2023). "We expanded our LiCor quantification analysis to include melanoma (A375) and colorectal (HT29) cells with BRAFV600E and a pancreatic cancer cell line with KRAS mutation (Capan-1)." (PMID 37018014, 2023). "Approximately 90% of pancreatic cancers harbor KRAS mutations, most commonly the G12D mutation 86,87." (PMID 37705755, 2023).
pancreatic cancer (continued). "Oncogenic KRAS point mutations lead to the permanent activation of KRAS-dependent pathways and have been identified in multiple types of cancer, most notably in pancreatic cancer, non-small cell lung cancer (NSCLC), and CRC." (PMID 37569406, 2023). "In this study, we used KRAS-mutated pancreatic cancer cells to explore its underlying mechanism by KV treatment." (PMID 37174108, 2023). "KRAS is a mutation in 90% of pancreatic cancer patients during which a substitution in the 12th amino acid (replacement of glycine with aspartate) has occurred (KRASG12D), and this mutation plays an essential role in tumor proliferation and metastasis." (PMID 37287924, 2023). "At the molecular level, heterogeneous oncogenic and loss-of-function mutations in tumor suppressors, in which KRAS variants are the most frequent, characterize pancreatic cancer cells." (PMID 37835519, 2023). "After verifying that the seven gene expression levels in different KRAS-mutated pancreatic cancer cell lines were similar to that in the model, we screened potential drugs related to the risk score." (PMID 38268915, 2023). "Although further studies are needed to determine the anticancer activity of this approach, this case suggests the major driver mutations of KRAS in pancreatic cancer can be targeted with T cell therapy." (PMID 37366887, 2023). "Although a positive correlation between KRAS mutation and PD-L1 expression has been observed in lung and pancreatic cancer, PD-L1 expression has been associated with reduced frequency of KRAS mutation in CRC." (PMID 37670322, 2023). "EVs have also been used to deliver CRISPR/Cas9 vector, coding for Cas9 plasmid and sgRNA specific for the KRAS G12D mutation, to disrupt KRAS activity at the gene level in in vitro and in vivo pancreatic cancer models." (PMID 37376135, 2023). "In this regard, pancreatic cancers, as the most lethal cancer with frequent mutations in KRAS, have a 5-year survival rate of approximately 10 %." (PMID 36313934, 2023). "Tumour-associated macrophages (TAMs) influence early stages of pancreatic tumour formation, activating KRAS-driven PDACs." (PMID 38273826, 2023). "It was shown to suppress proliferation of pancreatic cancer cells with mutated KRas and also reduced clone formation, invasion and migration of cells with mutated K-Ras." (PMID 37355668, 2023). "The two most common genetic alterations in pancreatic cancer are mutations in the Kirsten rat sarcoma viral (KRAS) oncogene and inactivation of SMAD4." (PMID 36902253, 2023). "WEE1 is the key kinase and the direct target of CHK1, and its expression is enhanced by KRAS mutation, as shown in pancreatic cancer cells." (PMID 36313934, 2023). "KRAS mutations were observed in colorectal or pancreatic cancer patients, and PIK3CA mutations mainly occurred in breast cancer and uterine cancer." (PMID 36910668, 2023). "About 30% of tumors have KRAS mutations, including 90% of pancreatic cancers, 30–40% of colorectal cancers, and 15%-20% of lung cancers." (PMID 37686343, 2023). "Pancreatic ductal adenocarcinoma (PDA), the most common type of pancreatic cancer, is almost invariably associated with oncogenic mutations in the KRAS gene." (PMID 36239683, 2023). "Exosomes have been utilized in numerous studies as delivery methods, and the oncogenic KRAS mutation is prevalent in pancreatic cancer." (PMID 37405480, 2023).
pancreatic cancer (continued). "This ADC contained the MMAE payload and was able to overcome EGFR mAb-resistance associated with KRAS mutation, which is present in almost all pancreatic cancers." (PMID 37880707, 2023). "KRAS is of special interest in pancreatic carcinoma since more than 90% of pancreatic carcinomas and even non-invasive, low-grade dysplasia PanINs show a KRAS mutation." (PMID 37511945, 2023). "SEMA3C expression was significantly higher in pancreatic cancer cell lines derived from the KRAS G12D mutation mice than that from the WT mice." (PMID 35785187, 2022). "Oncogenic KRAS mutations are a hallmark of cancer, being a very frequent event in many cancers, including pancreatic cancers (90%), CRCs (30–50%) and lung cancers, especially non-small-cell lung cancer (NSCLC) (15–20%)." (PMID 35883626, 2022). "Macropinocytosis enables pancreatic cancer cells with activated KRAS and deficient PTEN to overcome mTOR inhibitor resistance." (PMID 35177645, 2022). "Previous studies reported similar prevalence of KRAS mutation in hereditary pancreatic cancer and sporadic pancreatic cancer." (PMID 35163129, 2022). "It was indicated that there was another mechanism independently of KRAS mutation subtypes to explain the different responses of pancreatic cancer cells to MEKi." (PMID 35806187, 2022). "ERH knockdown blocks the cell cycle procession in the G2/M phase; this is especially obvious in human Kirsten rat sarcoma viral oncogene homolog (KRAS) mutation-related tumors (such as colorectal, lung and pancreatic cancer)." (PMID 35677162, 2022). "Here, three commonly‐seen KRAS mutations (i.e., G12D, G12V, and G12R)[17b] were detected in majority of the pancreatic cancer patients and correlated with KRAS mutation status of the matched tissues." (PMID 35486030, 2022). "It was found that the KRAS mutant allele fraction (MAF) in ctDNA plays an important role in the diagnosis of pancreatic cancer." (PMID 36551512, 2022). "One patient with pancreatic cancer showed mutations in both the KRAS and BRAF genes, despite previous evidence that these mutations are mutually exclusive due to overlapping functionality." (PMID 35338679, 2022). "Among KRAS mutations, KRAS-G12C mutation is a single point mutation with a glycine-to-cysteine substitution at codon 12, which can be observed in colorectal and pancreatic cancers, and is particularly prevalent in non-small cell lung cancer (NSCLC)." (PMID 35281897, 2022). "mRNA-5671 encodes mutated KRAS to treat colorectal, NSCLC and pancreatic cancers induced by one of four of the most common cancer-driving KRAS mutations (G12D, G12V, G13D and G12C)." (PMID 35603213, 2022). "We adopted this streamlined workflow to quantitatively detect gene alterations (i.e., Ewing sarcoma protein (EWS) gene rearrangements in Ewing sarcoma and KRAS mutations in pancreatic cancer patients." (PMID 35486030, 2022). "It has been demonstrated that after silencing the KRAS gene in pancreatic cancer cell lines containing KRAS mutations using short hairpin RNAs (shRNAs), some of the cell lines still survive, exhibiting dependence on PI3K." (PMID 36291766, 2022). "KRAS mutations are associated with a poor prognosis in general, notably in colorectal and pancreatic cancers." (PMID 35573474, 2022). "Our study aimed to investigate the role of the error-prone DNA double-strand breaks (DSBs) repair pathway, alt-EJ, in the presence of the KRAS G12D mutation in pancreatic cancer development." (PMID 36077614, 2022).
pancreatic cancer (continued). "Approximately 32 recurrently mutated genes in pancreatic cancer that aggregate into 10 core pathways have been reported: KRAS, TGF-β, WNT, NOTCH, ROBO/SLIT signaling, G1/S transition, SWI-SNF, chromatin modification, DNA repair, and RNA processing." (PMID 35664782, 2022). "It has also become clear that ADAM17 is important in cancers mediated by mutations in KRAS, which are the most frequent oncogenic mutations in human cancers, particularly in lung, colorectal and pancreatic tumours." (PMID 35971826, 2022). "KRAS mutations are dominant in lung, colorectal, and pancreatic cancers with various types of mutations." (PMID 36430528, 2022). "Mutated KRAS has been implicated in the development of most pancreatic cancers and is correlated with a worse prognosis for the patient." (PMID 35269876, 2022). "KRAS mutations, present in about 95% of pancreatic cancers, lead to the robust activation of the ERK MAPK and AKT signaling." (PMID 35203351, 2022). "Mutant RNF43 almost exclusively occurs along with abnormal KRAS and therefore, KRAS mutation is likely required for RNF43 mutation‐associated pancreatic cancer development." (PMID 35229994, 2022). "KRAS is the most frequently mutated gene in pancreatic cancer, and the most common mutation sites are c.35 > A, p.G12D and c.38G > A, p.G13D." (PMID 36551512, 2022). "KRAS is most commonly mutated in pancreatic cancer (90-95%) where it results in overexpression and activation of KRAS-driven oncogenic signalling that often contributes to tumorigenesis." (PMID 36619305, 2022). "These cells harbor the most frequent KRAS mutation that occurs in pancreatic cancer (G12D) and demonstrate moderate addiction to KRAS signaling that is comparable to the Panc1 cells." (PMID 36011352, 2022). "Pancreatitis associated with pancreatic tissue injury combined with KRAS mutation can also significantly accelerate the occurrence of early pancreatic cancer." (PMID 35965507, 2022). "KRAS is the most mutated oncogene in human cancers, with the highest frequency in pancreatic cancer (about 100%)." (PMID 36077614, 2022). "KRAS mutation has been confirmed as the primary contributor to pancreatic cancer carcinogenesis, being mutated in ~ 95% of pancreatic neoplasias." (PMID 35508982, 2022). "The KRAS G12D mutation is frequent in pancreatic cancer which makes targeting KRAS with the G12D mutation more prospective than the other mutations in pancreatic cancer therapy." (PMID 35785187, 2022). "In pancreatic cancer KRAS mutation reprograms glucose metabolism, upregulating the expression of serine-glycine pathway enzymes and sustaining tumor cells grow under serine starvation." (PMID 35619118, 2022). "It is a biodegradable implant containing a siRNA that targets the mRNA of the mutated KRAS oncogene, which can be surgically embedded in pancreatic tumors." (PMID 35269876, 2022). "These exploratory results need to be further validated and support the development of clinical trials in pancreatic cancer to uniquely target KRAS mutation variants within context-specific signaling networks." (PMID 36124727, 2022).
pancreatic cancer (continued). "For instance, it is interesting to observe how the KRAS gene, which is frequently mutated in pancreatic tumors, is able to regulate the autophagy pathway via the activation of several signaling pathways." (PMID 36558998, 2022). "KRAS genes are responsible for several types of cancer, and 90% of pancreatic cancer cases are directly attributable to KRAS mutations." (PMID 35409064, 2022). "In pancreatic cancer, exosomes derived from normal fibroblast-like mesenchymal cells were engineered to carry siRNA or shRNA specific to oncogenic KRAS, which is a common mutation in pancreatic cancer." (PMID 36361760, 2022). "Most cases of pancreatic cancer have mutations in the KRAS gene at the time of diagnosis (>80% of cases)." (PMID 35409064, 2022). "For example, EGFR mutation was presented in plasma exosomes from lung cancer and cerebrospinal fluid EVs from glioblastoma, and KRAS mutation was presented in plasma exosomes from pancreatic cancer and colorectal cancer." (PMID 35813192, 2022). "In pancreatic cancer, KRAS mutation is often the initiating genetic event leading to pancreatic intraepithelial neoplasms." (PMID 36284306, 2022). "We confirmed this observation that the KRAS G12D mutation can lead to increased KRAS expression level in pancreatic cancer patient samples." (PMID 35785187, 2022). "In pancreatic ductal carcinoma (PDAC), the most common subtype of pancreatic cancer, KRAS is the most predominant mutated gene (more than 80%)." (PMID 36291766, 2022). "Pancreatic cancer has the highest frequency of KRAS mutations but the prevailing KRAS G12D mutation is difficult to target." (PMID 36048281, 2022). "An ongoing phase I/II clinical trial is investigating transfer of T-cells engineered to express a G12D specific murine T-cell receptor (TCR) in HLA-A*11:01 patients with solid tumors, including pancreatic cancer, harboring the KRAS G12D mutation (NCT03745326)." (PMID 36531078, 2022). "Expression of TAGLN has been implicated with KRAS signaling in promoting proliferation in pancreatic cancer, KRAS mutations being the most frequent aberration in MOC." (PMID 36222710, 2022). "KRAS mutation is an oncogenic driver in solid tumors, including but not limited to pancreatic cancer, where KRAS mutation-induced macropinocytosis has been studied relatively earlier and more comprehensively." (PMID 35154489, 2022). "Taken together, it appears that various metabolic pathway abnormalities occur downstream of the KRAS mutation in pancreatic cancer, which results in the generation of substances that affect the odorant behaviors of nematodes." (PMID 35723350, 2022). "Most pancreatic cancers develop slowly from a premalignant lesion of pancreatic intraepithelial neoplasia (PanIN) which is associated with acquisition of the KRAS mutation." (PMID 35326559, 2022). "Downregulation of TDG is verified in pancreatic cancer cells with KRAS mutations, in contrast to those expressing the wild-type isoform of KRAS." (PMID 35883626, 2022). "After decades of dedication, scientists gradually unraveled the pivotal role of the classical oncogene KRAS and the activation of its mutation in pancreatic cancer." (PMID 36186449, 2022). "In fact, KRAS mutant colon tumors are demonstrated to be associated with an increased expression of glutamine and glycolytic metabolic proteins, while KRAS mutant pancreatic tumor showed reprogrammed glutamine metabolism." (PMID 35883626, 2022). "The small GTPase KRAS is frequently mutated in pancreatic cancer and its cooperation with the transcription factor MYC is essential for malignant transformation." (PMID 36581205, 2022). "We discovered a gene named SEMA3C was highly expressed in pancreatic cancer cell lines and patients with a G12D mutation in KRAS." (PMID 35785187, 2022).